TNF (tumor necrosis factor)
Diseases named in the same sentence as TNF in open-access papers (continued):
Sharing a sentence is not in itself a finding about the gene and the disease.
iron deficiency (52 papers, 2010 to 2025). "Searches have examined the pathophysiological processes of iron deficiency in inflammatory conditions, showing that it is triggered by pro‐inflammatory cytokines (IL‐6, IL‐1, TNF‐α)." (PMID 40637365, 2025). "LPS increased CYBRD1 (p < 0.001) and IL8 (p = 0.004) and tended to elevate TLR4 and TNF expression (p ≤ 0.07), while iron deficiency upregulated IL8 expression (p < 0.001)." (PMID 41295277, 2025). "Dietary iron restriction inhibits the pro-inflammatory response of peritoneal cells to M. leprae in vitro - In our study, iron deficiency resulted in lower secretion of IL-6 and TNF by peritoneal cells infected in vitro with M. leprae." (PMID 39166620, 2024). "The secretion of TNF by peritoneal cells from iron deficiency stimulated with M. leprae was lower than the standard diet (p = 0.0007) and iron-supplemented diet (p = 0.009)." (PMID 39166620, 2024). "In this study, iron deficiency also decreased the levels of inflammatory factors such as TNF-α, IFN-γ, IL-6 and IL-1β in the serum of neonatal pigs." (PMID 39127747, 2024). "Magnesium deficiency in rats causes cardiac dysfunction and inflammation, increasing the production of TNF-α, IL-1, and IL-6." (PMID 35056870, 2022). "Magnesium deficiency in a rat model of endotoxin shock also promoted the secretion of proinflammatory cytokines, including interleukin-6, tumor necrosis factor-alpha, and interleukin-1-beta, which intensify the failure of various organs." (PMID 36424547, 2022). "Magnesium deficiency increases the ability of macrophages to produce inflammatory cytokines, especially TNF-α, IL-1, and IL-6, resulting in the development of low-grade inflammation." (PMID 35056870, 2022). "For example, intracellular iron deficiency induced by either iron chelation or overexpression of ferroportin, the only known iron exporter, attenuated LPS-stimulated TNFα and IL-6 production in peritoneal macrophages." (PMID 35956279, 2022). "The concentration of TNF-α in the ID group was significantly increased (P < 0.05), indicating that iron deficiency caused an inflammatory response in the body." (PMID 36159485, 2022). "The treatment with anti-TNF-alpha agents has been shown to improve iron deficiency by improving erythropoiesis, implicating a role for TNF-alpha in the development of IDA patients." (PMID 34836263, 2021). "FTH1 and FTL lead iron deficiency will start cascade events to proliferate gene activation and tumor necrosis factor α (TNFα) tolerance." (PMID 33324555, 2020). "Taken together, upregulation of TNF-α/NF-κB signaling and the associated increase in IL-1β are underlying downstream mechanisms of magnesium deficiency in the CYP-induced cystitis model." (PMID 32241292, 2020). "The iron deficiency and the pro-inflammatory cytokines/inflammation (IL-6, IL-1β and TNFα) act as positive regulators." (PMID 31172340, 2019). "Several studies have shown that magnesium deficiency increases the production of many pro-inflammatory cytokines (such as TNF-α, IL-6) and that this effect is accompanied by the sensitization of cells such as neutrophils, macrophages and endothelial cells." (PMID 29467509, 2018). "It is interesting to highlight that treatment with antitumor necrosis factor-alpha agents has been shown to improve iron deficiency by improving erythropoiesis, implicating a role for TNF-alpha in development of ACD and/or IDA in IBD patients." (PMID 25705682, 2015). "Moreover, chronic exposure to TNF-α in intestinal cells can downregulate the expression of iron transporters, thereby impairing iron absorption and leading to iron deficiency." (PMID 41141252, 2025). "Moreover, magnesium deficiency is associated with inflammatory responses mediated by calcium, N-methyl-D-aspartate, and tumor necrosis factor-alpha, as well as increases in C-reactive protein (CRP)." (PMID 41019555, 2025). "Iron deficiency could potentially influence the expression of cytokines such as IL-6, IL-1, TNF-α, and IFN-γ, contributing to tissue damage." (PMID 39161911, 2024).
iron deficiency (continued). "Recent research has shown that iron deficiency enhances mitoROS production and mitoROS-dependent NETosis, impairing the functional efficacy of neutrophils in plasma and suppressing the production of inflammatory cytokines TNF-α, IL-6, and IL-12." (PMID 39127747, 2024). "Magnesium deficiency has also been associated with low-grade systemic inflammation, and has been shown to increase pro-inflammatory cytokines: tumor necrosis factor-alpha (TNF-α) and interleukin 1 (IL-1)." (PMID 34684376, 2021). "Because of chronic blood loss, functional iron deficiency, and inflammation imbalance in terms of an increased expression of interleukin and tumor necrosis factor, the malignancy induces a low hemoglobin count, which is a common complication for cancer patients." (PMID 34485155, 2021). "Taken together, L-TAMS attenuated mechanical allodynia, depressive-like behavior, and memory deficits in CYP-induced cystitis model rats through prevention of magnesium deficiency and abnormal regulation of TNF-α/NF-κB signaling, IL-1β, and the NR2B subunit in the SDH and hippocampus." (PMID 32241292, 2020). "Next, we explored whether TNF-α/NF-κB signaling is associated with magnesium deficiency in vivo." (PMID 32241292, 2020). "It has been stated that iron deficiency increases HIF-1α protein expression, which upregulates the expression of IL-6 and TNFα." (PMID 37513518, 2023). "In a cohort of Gambian children, the TNF−308 AA genotype (which is associated with higher TNF-α transcription compared with TNF−308 AG and TNF−308 GG genotypes) was strongly associated with increased risk of iron deficiency and IDA." (PMID 30275421, 2018). "While levels of TNF, IFN-γ and IL-1β (type I) and IL-10 and IL-13 (type II) seemed decreased in iron deficiency anaemia, the levels of IL-12 and IL-5 appeared increased." (PMID 20546583, 2010). "Indeed, hepcidin, a good iron-deficiency biomarker, was found to be significantly decreased in IBD patients who responded to the anti-TNF-α therapy." (PMID 38257172, 2024). "Ferroportin-mediated iron depletion of Hfe-/- macrophages has been demonstrated to lead to decreased production of TNF-α and interleukin (IL-6) in vitro, while altered inflammatory cytokine levels have variably been reported with HFE variants and in iron deficiency." (PMID 33057367, 2020). "Oral application of L-TAMS substantially reversed the magnesium deficiency and upregulation of TNF-α/NF-κB signaling and IL-1β and normalized the expression of NR2B." (PMID 32241292, 2020). "In the present study, we demonstrated that iron deficiency led to an enhanced pro-inflammatory response, resulting in a marked increase in serum contents of the inflammatory cytokines, IL-1β, IL-4, IL-6, TGF-β1, and TNF-α and a trend towards increased contents of IL-12 and GM-CSF." (PMID 39296492, 2024).
Miscarriage (52 papers, 2012 to 2026). A pregnancy that ends at a stage in which the fetus is incapable of surviving on its own, defined as the spontaneous loss of a fetus before the 22th week of pregnancy. "TNF-α inhibitors have been associated with few adverse effects among treated pregnant women, like miscarriage, which poses a significant health concern among women." (PMID 40979093, 2025). "As an indicator of systemic inflammation and stress, PLR offers a more accessible and cost‐effective alternative to other serum markers associated with miscarriage, such as periodin, Th‐1, TNF‐α, and Th‐17." (PMID 39778007, 2025). "TNF-α levels rise throughout pregnancy, and elevated levels are associated with miscarriage, foetal loss, pre‐eclampsia, and preterm birth." (PMID 40843056, 2025). "The increase in systemic TNF-α levels during pregnancy is associated with miscarriages, late fetal losses, PE, and preterm birth." (PMID 37446111, 2023). "The increased production of the cytokines IFNγ and TNFα by dNK cells and placental macrophages is associated with the development of miscarriage." (PMID 35216502, 2022). "The TNF-α -308 GA variant is also considered as a risk factor for miscarriages." (PMID 32341828, 2020). "The underlying mechanism of Waddlia-associated miscarriage may involve bacterial proteins, such as heat-shock protein 60, or production of inflammatory cytokines, such as tumor necrosis factor-α." (PMID 24564950, 2014). "TNF-α inhibitors have been floated as potential interventions against early contractions that lead to premature miscarriage." (PMID 40979093, 2025). "The serum of miscarriage patients has been shown to contain significantly higher levels of specific inflammatory cytokines (IL-2, IL-17A, IL-17F, TNF-α, and IFN-γ)." (PMID 39203483, 2024). "Results showed that miscarriage cases had significantly lower levels of IL-1β, TNF-α, V, Cu, Zn, and Se compared to successful live birth cases." (PMID 39683462, 2024). "Studies have shown that when miscarriage occurs, maternal expression of Th1-type cytokines such as TNF-α is elevated, whereas the expression of Th2-type cytokines such as IL-4 was downregulated." (PMID 39351087, 2024). "At the same time, it is known that the secretion of TNFα, as well as IFNγ, by dNK cells is increased in spontaneous miscarriage." (PMID 35216502, 2022). "In contrast, mitogen-activated PBMCs from RPL women with successful pregnancy outcomes exhibited comparable TNF-α levels to those with miscarriages but lower than normal pregnant females." (PMID 36613575, 2022). "We showed a positive correlation of Il-4 with both INF-γ as well as with Il-1β and TNF-α in the case of miscarriage." (PMID 34444287, 2021). "In most publications on spontaneous and recurrent miscarriages, serum TNF-α levels were significantly higher in the studied groups than in women with normal pregnancy." (PMID 34444287, 2021). "Increased placental levels of TNF-α increases abortion rates, and blockade of TNF-α has been shown to prevent stress-induced miscarriage in mice." (PMID 26837816, 2016). "Circulating levels of TNF-α are higher both in animals and humans with a miscarriage compared to those with a successful pregnancy, suggesting that this cytokine is exclusively harmful for pregnancy." (PMID 26837816, 2016). "In parallel, Tim-3−PD-1− dCD8+ T cells in miscarriage produced lower amounts of Th2-type cytokines, but more TNF-α." (PMID 25950468, 2015). "In the present study, we also found that in early pregnancy (i.e., before 14 weeks), the amount of TNFα and IL-10 secreted in vitro by villous tissue from sporadic miscarriage was lower in the group with a normal karyotype." (PMID 21977049, 2012). "Yet, the profiles from day ET+16 indicated a significant difference concerning an increase of the pro-inflammatory cytokines IL-17, IFN-γ and TNF-α in the miscarriage group, but a sustained increase of anti-inflammatory cytokines IL-10 and TGF-β1 in the live birth group." (PMID 37744353, 2023).
Miscarriage (continued). "Interestingly, the circulating levels of TNF-α are higher in case of miscarriage compared to those reported in a successful pregnancy indicating that abnormal TNF-α levels adversely affect the progression of pregnancy." (PMID 33838693, 2021). "Genetic susceptibility may be involved in the onset of recurrent miscarriage and play an important role in the occurrence and development of RM 30; such genes include FOXP3, IL‐10, and TNF‐α." (PMID 31454102, 2019). "The TNF-α level is markedly elevated in the serum of women with recurrent spontaneous miscarriage." (PMID 28851386, 2017). "TNF -238G > A, TNF -308G > A, IL1B -511 T > C, IL1B 3954C > T, IL6 -174G > C, IL6 -634C > G, IL10 -1082A > G and IFNG 874A > T polymorphisms were genotyped on 775 women with idiopathic recurrent miscarriage and 805 healthy parous control women." (PMID 29017513, 2017). "Other reports have noted low and non-detectable circulating levels of several cytokines including IL-1β, IL-6, IFN-γ and TNF-α and lack of consistent associations with miscarriage risk." (PMID 24699265, 2014). "Furthermore, in infected pregnant marmosets, cleaved caspase staining was widely observed from the endometrium to the placenta, and a certain level of TNFα was detected in the amniotic fluid, suggesting that apoptosis progressed in the endometrium and placenta, leading to miscarriage." (PMID 39998269, 2025). "Moreover, imbalanced expression of Th1/Th2/Th17 cytokines and significant elevation of interferon (IFN)-γ, tumor necrosis factor (TNF)-α, interleukin (IL)-6, and IL-17A levels in Chlamydia trachomatis (Ct)-positive recurrent miscarriage patients have been observed." (PMID 35604131, 2022). "In addition, inhibiting TNF-α reduces stress-induced miscarriage in mice." (PMID 36613575, 2022). "Moreover, we found that the fecal concentrations of 1, 4-Methylimidazoleacetic acid, and imidazolepropionic acid that were enriched in histidine metabolism were also significantly increased in the miscarriage group and aligned well with the increased IL-17, TNF-α, and IFN-γ in this group." (PMID 33731680, 2021). "In addition, decidual Tim-3−PD-1−CD8+ T cells from miscarriage produced more TNF-α." (PMID 25950468, 2015). "Cleaved-caspase was widely observed in the endometrial to placental region, and TNFα at 200 pg/mL was detected in the amniotic fluid, suggesting that apoptosis may progress in the endometrium and placenta, leading to decreased trophoblast function and miscarriage." (PMID 39998269, 2025). "TNF-α was also reported to inhibit trophoblast invasion and elevated TNF-α levels were identified in women who experienced miscarriage." (PMID 37305407, 2023). "Multiplex analysis revealed markedly increased serum levels of IL-2, IL-17A, IL-17F, tumor necrosis factor-α (TNF-α), and IFN-γ in miscarriage patients than those in the controls." (PMID 33731680, 2021). "The current study also found that serum levels of IL-2, IL-17A, IL-17F, TNF-α, and IFN-γ were markedly increased in miscarriage patients compared to the controls." (PMID 33731680, 2021). "Here we report that IL-2, IL-17A, IL-17F, TNF-α, and IFN-γ are significantly increased in serum of miscarriage patients." (PMID 33731680, 2021). "Whitcomb tested the serum of women 10 days before miscarriage, and found low levels of several pro-inflammatory cytokines, IL-1β, IL-4, IL-6, IFN-γ and TNF- α, which confirms our findings." (PMID 34300281, 2021). "Compared with the control group, the IL-2, IL-17A, IL-17, TNF-α, and IFN-γ levels of serum were increased significantly in the miscarriage group." (PMID 34966824, 2021). "Th1 cytokine levels in women with miscarriage compared to the control group reached slightly higher values for INF-γ, Il-1β and slightly lower for Il-6 and TNF-α." (PMID 34444287, 2021). "Studies done with lymphocytes isolated from women with recurrent miscarriage indicate that dydrogesterone inhibits the production of INF-γ, TNFα, IL-4, and IL-6 modifying the Th1/Th2 ratio." (PMID 26446923, 2015).
Miscarriage (continued). "Moreover, in normal pregnancy, Tim-3+PD-1+ CD8+ T cells, the number of which was more than that in miscarriage, produced higher levels of IL-4 and IL-10 but lower levels of IFN-γ and TNF-α." (PMID 25950468, 2015). "Therefore, cytokines INF-γ and TNF-α should be responsible for altered expression of CFTR and ENaC-α in decidua of miscarriage." (PMID 24914548, 2014). "In the miscarriage model, ML345 not only decreased IL-1β levels but also reduced IL-6 and TNF, which are independent of NLRP3." (PMID 41231359, 2025). "The increase in activating isoforms did not correlate with higher expression of TNF-α, IFN-γ, IL-10, and placental growth factor mRNAs in the placental tissue of those women who experienced sporadic miscarriage, as compared to those that had undergone elective abortions." (PMID 28424697, 2017).
neutropenia (52 papers, 2004 to 2026). A decrease in the number of neutrophils found in the blood. "Some reports have also linked anti-granulocyte antibody-related neutropenia to exposure to anti-TNF agents." (PMID 38883009, 2024). "In the present work, we showed that while the inhibition of IL-6R is associated with neutropenia and monocytosis, different anti-TNFα therapies cause a wide spectrum of changes in hematological variables." (PMID 35651659, 2022). "In this context, all biotherapies on the market in the USA and Europe have also been associated with neutropenia (especially well-documented for TNF-α inhibitors, tocilizumab, rituximab, and alemtuzumab)." (PMID 31480527, 2019). "Outside the context of oncology, biotherapies have been reported as being the cause of early and transient Grade 1–2 neutropenia in 10–15% of the treated patients, often with TNF-α inhibitors, tocilizumab, rituximab, and alemtuzumab." (PMID 31480527, 2019). "Clinically significant neutropenia and associated infection are rare with anti-TNF therapies and also with rituximab, but the regular control of blood count is advisable." (PMID 24620738, 2014). "However, increased docetaxel concentration resulted in neutropenia and was associated with the upregulation of NF-κB and TNF-α." (PMID 38730660, 2024). "The role of XIAP in human neutrophils remains unclear; Wicki reported that loss of XIAP facilitates the switch to TNFα-induced necroptosis in mouse neutrophils; hence, the cause of neutropenia in our patient deserves further study." (PMID 31754776, 2020). "CAR-T–associated CRS is characterized by an increase in cytokines IFN-γ and TNF-α, while neutropenia is characterized by a decrease in IL-17A and G-CSF." (PMID 41165751, 2026). "All donkeys developed typical features of SIRS such as tachycardia, fever, leukopenia and neutropenia, and an increase in plasma TNFα concentration from 30 min post-LPS infusion (data previously published)." (PMID 39765564, 2024). "While treatment with anti-TNF agents is sufficient for most patients with a vascular phenotype, anti-TNF has little impact on severe neutropenia or pancytopenia." (PMID 35095905, 2021). "Patients with hematologic and immune dysregulation had a varied response to anti-TNF therapy with features such as neutropenia, PRCA, and hypogammaglobulinemia demonstrating the least response to TNF inhibitors." (PMID 35095905, 2021). "The incidence of grade 3/4 leucopenia and neutropenia during CCRT were higher in the TNF + N group than those in the TPF + P group (36.3% vs. 22.1%, P = 0.019; 31.0% vs. 16.8%, P = 0.013, respectively)." (PMID 33123269, 2020). "Lipopolysaccharide induced fever, leukopenia, and neutropenia of similar magnitude in both groups, but meloxicam attenuated increases in plasma lactate, tumor necrosis factor‐alpha (TNFα), and interleukin 1β concentrations compared to controls." (PMID 32463537, 2020). "A few biologic drugs such as TNF-α, IL6R, and CD20 inhibitors, can cause complications of neutropenia." (PMID 30884802, 2019). "Only a few case reports of Grade 3–4 neutropenia have been reported to date with anti-TNF-α therapy, tocilizumab therapy, and IL1 inhibitors." (PMID 31480527, 2019). "In this setting, transitory Grade 1–2 neutropenia related to biotherapy is relatively common with several biotherapies (e.g., TNF-alpha inhibitors, IL6 inhibitors, and anti-CD52 agents)." (PMID 31480527, 2019). "Of these patients, 69 (18.8%) had at least one episode of neutropenia during TNF-α inhibitor treatment." (PMID 31480527, 2019). "An approximate 10% prevalence of such neutropenia has been reported with several of these biotherapies (e.g., TNF-alpha inhibitors, IL6 inhibitors, and anti-CD52 agents)." (PMID 31480527, 2019). "In some patients, it has been seen that anti-TNF-α exposure during pregnancy can lead to neutropenia." (PMID 28983301, 2017).